LGALS3 (galectin 3)
Diseases named in the same sentence as LGALS3 in open-access papers (continued):
Sharing a sentence is not in itself a finding about the gene and the disease.
cancer (continued). "Galectin-3 was the most specific marker for the diagnosis of carcinoma (90.3%)." (PMID 34711014, 2021). "Intriguingly, retinoic acid treatment inhibited LGALS3 expression in carcinoma cells, suggesting that reduced levels of retinoic acid could promote LGALS3 upregulation." (PMID 34794390, 2021). "Considering the key function of galectin-3, IL-6, chemerin and pentraxin-3 in inflammation and cancer, the altered secretome may be a consequence of malignant cell transformation." (PMID 33066326, 2020). "Therefore, developing a formulation for cancer therapeutics to target galectin-3 for intra-tumoral purposes is ideal." (PMID 32235765, 2020). "Cancer cells express Galectin-3, limiting T-cell mediated immunity against cancer cells." (PMID 32908213, 2020). "Thus, the peptides are most likely not binding to antigens that are expressed by several different types of cancer, such as the Thomsen–Friedenreich (TF) antigen, galectin-3, or the epidermal growth factor receptor (EGFR)." (PMID 32380649, 2020). "By binding to Galectin-3, pectins can stimulate immunity against cancer cells." (PMID 32908213, 2020). "The role of Galectin-3 in cancer stem-like cells (CSCs) is poorly investigated." (PMID 33013832, 2020). "Indeed, in normal and cancer epithelial cells deriving from the digestive tract, Galectin-3 is localised at the interface between ER and outer mitochondrial membrane." (PMID 32398681, 2020). "In addition to cancer cells, Galectin-3 is expressed on immune cells, such as monocytes, macrophages, DCs, neutrophils and epithelial cells." (PMID 32908213, 2020). "This could increase cellular motility and metastasis while protecting cancer cells from proapoptotic events and anoikis (a function of intracellular Galectin-3)." (PMID 31949431, 2019). "Notably recent studies have suggested that the ligands of galectin-3 demonstrated relatively good performance for the diagnosis of cancer." (PMID 31832021, 2019). "Thus, the C. japonicus enzyme has been regarded as the most promising candidate for the production at scale of galactose-rich PGOs with PD < 4 for its potential application for recognition to cancer cells (i.e., as inhibitor of pro-metastasic Galectin 3)." (PMID 31067636, 2019). "Galectin-3 (gal-3) is a glycoprotein that has a role in fibrosis, inflammation, and cancer." (PMID 31929803, 2019). "Galectin-3 plays a prominent role in the progression of cancer and fibrotic diseases." (PMID 31683865, 2019). "Galectin-3 is a carbohydrate binding protein which has important roles in cancer and immunity." (PMID 30778105, 2019). "Our results did suggest that galectin-3 play an oncogenic role in overall cancer patients." (PMID 30410421, 2018). "Galectin-3 (Gal-3) is recognized as a prognostic marker in several cancer types." (PMID 29373511, 2018). "Moreover, due to the wide activation of NF-κB in cancers, the efficiency of Galectin-3/TLR4/NF-κB/NEAT1 path should be compared with NF-κB activation induced by other factors in vitro and in vivo." (PMID 29788922, 2018). "Firstly, different studies had their own varied expression cut-off values, which brought many difficulties for us to define the standard cutoff value, resulting in bias in the results of the effectiveness of galectin-3 as a prognostic factor in cancer patients." (PMID 30410421, 2018). "Hence, this meta-analysis was performed to clarify the precise predictive value of galectin-3 in various cancers." (PMID 30410421, 2018). "Likewise, the expression level of galectin-3 was increased significantly in the sera of patients with various cancers and mediates MDR." (PMID 29389859, 2018). "Secondly, heterogeneity existed in the total OS and DFS/RFS/PFS group and it was likely due to the different characteristics of the patients, such as the age, cancer type, different method in detecting samples and the varied cut-off values of galectin-3 expression." (PMID 30410421, 2018).
cancer (continued). "As presented by our results, we could easily find that there might be the existence of significant heterogeneity of elevated galectin-3 expression in the overall cancer patients." (PMID 30410421, 2018). "However, there were also some attempts to decrease galectin-3 expression and sensitize cancer cells to chemotherapeutic agents by natural dietary phytochemicals." (PMID 30267152, 2018). "In addition, we observed galectin-3 expression at the interface between cancer and lymphocyte aggregates." (PMID 30254278, 2018). "However, the definite role of galectin-3 in various human malignant neoplasms remained inconsistent." (PMID 30410421, 2018). "Galectin-3 expression impaired the cancer suppressive effects of miR-128." (PMID 28146425, 2017). "Galectin-3 overexpression has been involved in several human cancer types." (PMID 28146425, 2017). "Understanding the mechanisms of how Galectin-3 promotes cancer cell motility may help to fulfill this goal." (PMID 29254179, 2017). "The top up-regulated genes included glycoprotein non-metastatic b (Gpnmb) and Galectin-3 (Lgals3), both of which have been implicated in several cancers when overexpressed." (PMID 29222421, 2017). "Galectin-3 overexpression was observed in hypoxic fields of cancer tissues." (PMID 29254179, 2017). "While the anaplastic cancer tissue showed an extensive but weak Galectin-3 expression level." (PMID 29254179, 2017). "Cell adhesion and proliferation due to galectin-3 may translate into pathological processes like fibrosis and cancer progression." (PMID 27089335, 2016). "Some cancer cells possessing galectin-3 advancement showed enhanced PI3K/AKT signaling." (PMID 26934444, 2016). "Moreover, galectin-3 can be released by cancer cells into extracellular environment, thus the level of galectin-3 in the serum of many types of cancer patients are higher than healthy controls." (PMID 27191983, 2016). "Galectin-3, which has already been identified as a component of extracellular vesicles deriving from dendritic cells, has also been known to impact on β-Catenin degradation in the context of cancer." (PMID 26752347, 2016). "Moreover, studies suggest galectin-3 regulates cancer progression, including cell proliferation, apoptosis, migration, and invasion." (PMID 27626163, 2016). "The relationship between the expression of galectin-3 and cancer behavior is controversial and the mechanisms controlling its expression remain unclear." (PMID 26222311, 2015). "The expression levels of galectin-3 mRNA in the Eca-109 cancer cells were quantified by qPCR." (PMID 25373317, 2015). "As the heparin derivatives E, E3 and F3 showed significant inhibition of galectin-3-mediated cancer cell-endothelial adhesion, these derivatives were tested for their impact on circulating galectin-3-mediated metastasis in an experimental mouse metastasis model." (PMID 26160844, 2015). "With regard to a possible mechanism of action, previous data on various tumors suggest that galectin-3 may mediate invasion and the migration of cancer cells via the Wnt/ β-catenin signaling pathway and Akt (Protein Kinase B) phosphorylation." (PMID 24708743, 2014). "Galectin-3 expression is frequently altered in cancers with divergent effects on tumor growth." (PMID 25256425, 2014). "The mRNA expression of galectin-1 and galectin-3 is significantly increased in RCC cancer tissue." (PMID 24708743, 2014). "Furthermore, an interaction between MUC1 on the surface of cancer cells and serum-localized galectin-3 promotes strong adhesion of tumor cells to the endothelial surface, thus promoting cancer cell metastasis." (PMID 24639126, 2014). "In cancer, there is often a change in intracellular localization of galectin-3." (PMID 24658839, 2014). "Despite galectin-3 expression in a variety of cell types and its involvement in several biological processes, this molecule raises special interest due to its remarkable role in regulating a broad range of cancer cell activities." (PMID 24982845, 2014).
cancer (continued). "Galectin-1 and Galectin-3 were most intensively studied in context of cancer." (PMID 24592356, 2014). "In this study, we have shown that the serum galectin-3 concentrations were uniformly higher in patients with metastatic PCa as compared to non-cancer control patients and could increase the reliability of the PSA blood test." (PMID 23625538, 2013). "In an attempt to determine if galectin-3 can serve as a complementary biomarker to PSA to reduce false negative/positive results for PCa, we analyzed galectin-3 levels in the blood of metastatic PCa patients and compared it to the levels of galectin-3 in non-cancer subjects." (PMID 23625538, 2013). "Although the anti-apoptotic role and mechanism of galectin-3 in cancer drug resistance have been studied, the regulatory pathway and mechanism(s) of chemoresistance-associated proteins modulated by galectin-3 in MDR cancer cells have not been fully elucidated." (PMID 24303084, 2013). "The importance of Galectin-3 protein is manifested by its many effects on cancer cells." (PMID 23401782, 2013). "The levels of galectin-3 in the sera of 8 non-cancer controls are all lower than 0.07 ng/ml." (PMID 23625538, 2013). "In addition to understanding the role of galectin-3 in cancer drug resistance, we further examined the key role of shGal-3 in apoptosis induction." (PMID 24303084, 2013). "The cancer-free control patients have lower levels of galectin-3 in the serum." (PMID 23625538, 2013). "Changes in galectin-3 (Gal-3) expression are commonly seen in cancer and pre-cancerous conditions, and Gal-3 may be involved in the regulation of diverse cancer cell activities that contribute to tumourigenesis, cancer progression and metastasis." (PMID 24313993, 2013). "Thus, we compared galectin-3 levels obtained from sera of non-cancer urology patients to those of metastatic PCa patients." (PMID 23625538, 2013). "Finally, heat-modified pectin initiates apoptosis in cancer cells, in a galectin-3-independent manner." (PMID 24115933, 2013). "Plasma galectin-3 levels are even being considered as a marker of response to cancer treatment." (PMID 23056639, 2012). "A further candidate cancer stem cell molecule identified in our model was galectin-3." (PMID 23285151, 2012). "Recent observations in a cancer xenograft model indicates that inhibition of galectin-3, using synthetic lactulosyl-1-leucine combined with taxol, reduced lung metastases and increased metastases-free animals; a finding that points to increasing relevance of galectin-3 activities in human cancer." (PMID 22039439, 2011). "Translocation of galectin-3 into the nucleus may induce apoptosis and therefore defeat cancer cells." (PMID 21958686, 2011). "Cancer stroma angiogenesis may be promoted through matrix metalloproteinase cleavage of galectin-3 N-terminus in both in-vitro angiogenesis models and human cancer tissues." (PMID 22039439, 2011). "Therefore, d-(+)-galactose-conjugated SWCNTs are potentially useful electrochemical nanobiosensors for the cancer marker galectin-3." (PMID 21686160, 2011). "The present study used qRT-PCR to determine mRNA levels of galectin-3 and Beclin1 in human cancers." (PMID 22039439, 2011). "This suggests that expressions of galectin-3 may regulate or be related to autophagy in cancers and act as additional mode of influencing cancer progression." (PMID 22039439, 2011). "Summary of normalized galectin-3 mRNA levels in Normal and Cancer Tissues." (PMID 22039439, 2011). "Lung tissues had lower galectin-3 and higher Beclin1 in cancer compared to normal." (PMID 22039439, 2011). "In human cancers with high galectin-3 (presumed pro-apoptosis) and Beclin1, use of small molecule inhibition of galectin-3 to enhance treatment response may be beneficial." (PMID 22039439, 2011). "Normal and cancer tissues from the liver and lung had the lowest expressions of galectin-3." (PMID 22039439, 2011).
cancer (continued). "It seems to be interesting that galectin-3 expression could play different roles in another carcinomas." (PMID 22024187, 2011). "This, together with our earlier reports showing an enhanced cancer cell-endothelial adhesion also resulting from the galectin-3-MUC1 interaction, indicates that the increased circulation of galectin-3 in the bloodstream of cancer patients promotes several important steps of the metastatic cascade." (PMID 20565834, 2010). "Galectins, especially galectin-3, are modulators of cancer cell adhesion and invasiveness." (PMID 20831833, 2010). "However, a significantly stronger expression of galectin-3 in cancer tissues was observed only in papillary and poorly differentiated adenocarcinoma." (PMID 23658855, 2010). "Interestingly, when galectin-3 was detected in the cancer cells, it was consistently excluded from the nucleus and only present in the cytoplasmic compartment." (PMID 23658855, 2010). "Galectin-3 immunostaining of any pattern was not related to grade or stage in cancers; mere cytoplasmic expression was associated with poor outcome." (PMID 23658855, 2010). "Because galectin-3 is cleavable by MMPs and is co-localized with active MMPs, antibodies recognizing cleaved and non-cleaved forms of galectin-3 can indicate the presence of active MMPs in a cancer." (PMID 23658855, 2010). "The higher expression of galectin-3 in TC and its focal staining (apical) pattern suggests that within the group of G1 carcinomas, galectin-3 expression varies according to histological type, and may correlate with prognosis and metastatic potential." (PMID 23658855, 2010). "The sensitivity for positive expression for all benign lesions versus malignant tumors was as follows: 10/44 (22.7%) versus 25/27 (92.6%) for galectin-3; 14/44 (31.8%) versus 23/27 (85%) for Ret; 12/44 (27.3%) versus 24/27 (88.8%) for HBME-1; and 13/44 (29.5%) versus 23/27 (85%) for CK19." (PMID 19826479, 2009). "Meanwhile, immune infiltration analysis revealed that expression of LGALS3 showed a significant positive association with several immune cell populations, involving CD4+ T cell, CD8+T cell, B cell, neutrophil, macrophage, dendritic cell, as well as cancer-associated fibroblasts (CAFs) within HCC." (PMID 38643145, 2024). "As our findings show that there is a significant proportion of LAG3+ CD8+ T-cell targeted by ligand LGALS3+ originating from mesenchymal cancer cells, we sought to further explore the link between LGALS3 and EMT to better elucidate how EMT could modulate CD8+ T-cell exhaustion." (PMID 38086828, 2023). "Thus, activation of PYK2 and GSK3 signalling in cancer cells by galectin-3 may itself influence cancer progression in addition to its effect through induction of protease secretion." (PMID 37055381, 2023). "Therefore, we investigated whether knockdown of BAP31 downregulates galectin-3 to inhibit the Wnt/β-catenin pathway and modulate 5-FU chemosensitivity and cancer stemness in CRC cells." (PMID 37762705, 2023). "Interestingly, galectin-3 also plays an extracellular role in controlling cancer growth." (PMID 37371482, 2023). "Moreover, the results of the CCK8 cell proliferation assay showed that the proliferation of cancer cells decreased significantly after LGALS3 knockdown, and the results of the transwell assay showed that LGALS3 knockdown significantly affected the migratory ability of cancer cells." (PMID 37180150, 2023). "We further tested whether recombinant galectin-3 could promote the migration of cancer cells." (PMID 38052804, 2023). "Increased proteolytic activity of CAKs and secretion of galectin 3 might impact cancer progression." (PMID 36123693, 2022). "Interestingly, studies have now demonstrated that the platelet GPVI/Syk activation may also promote metastasis through interaction with cancer cell-derived galectin-3." (PMID 36556013, 2022).
cancer (continued). "In this study, we conducted a series of in vitro and in vivo studies to test whether circulating PNA can, like circulating galectin-3, also interact with the blood vascular endothelium and affect endothelial secretion of cytokines relevant to cancer metastasis." (PMID 34223877, 2021). "Furthermore, other innate immune cells may also be involved in the complete picture of how galectin-3 regulates immunity against cancer." (PMID 34572756, 2021). "The extracellular galectin-3 protein participates in the tumorigenesis process by various mechanisms, including inflammation, cellular proliferation, angiogenesis, and progression to an overt metastatic state via cancer cell–endothelial adhesion in distant organs." (PMID 34959847, 2021). "These materials have a great potential for drug delivery in cancer treatment, due to their temperature response, small sizes, potential non-cytotoxicity evolving from its constituents, and the potential recognition of cancer cells via the Galactan-Galectin 3 interaction." (PMID 32967249, 2020). "In the current study, we observed that galectin-3 staining of the pancreatic tissue in probiotic treated mice was reduced compared with the mice not treated with probiotics, indicating that probiotics have the potential to suppress malignant cellular transformation and metastasis of cancer cells." (PMID 33255941, 2020). "Moreover, this was the first meta-analysis reporting the prognostic value of galectin-3 for cancers in the medical literature, which could provide some references for clinical work." (PMID 30410421, 2018). "Treatment targeting galectin-3 must also take into consideration the fact that galectin-3 promotes cancer and metastasis and that there is not a causal necessity between a protein being upregulated in a disease and the possibility to treat the disease by inhibiting the protein." (PMID 29950926, 2018). "Further, cancer cell extravasation and possible heterotypic intercellular communication between cancer cells and endothelial cells may be influenced by interactions with molecules such as N-cadherin or galectin-3 on endothelial cells." (PMID 28262832, 2017). "Furthermore, galectin-3 interacts with T antigens on MUC1 to promote cancer metastasis." (PMID 25762620, 2015). "In addition, galectin-3 also expresses polylactosamine-type N-glycans in cancer cells." (PMID 24715095, 2014). "Galectin-3, a member of the β-galactoside-binding lectin family, is thought to have a number of different biological roles, probably including the progression and metastasis of cancer through regulation of homotypic and heterotypic cell-cell and cell-matrix interactions." (PMID 25254965, 2014). "Galectin-3, a β-galactoside-binding protein, exhibits a variety of biological and pathological functions, including effects on RNA processing, cell growth, differentiation, adhesion, apoptosis, immune response, malignant transformation, metastasis, and cancer drug resistance." (PMID 24303084, 2013). "In the extracellular space, galectin-3 binds to a variety of extracellular matrix components like laminin, fibronectin, hensin, elastin, collagen IV and tenascin-C and -R, modulating cell-matrix dependent biological processes, such as adhesion and migration, in normal and cancer cells." (PMID 22216245, 2011). "Galectin-3, a member of the galectin family (galectins 1–15), has both anti- and pro-apoptotic effects, expressed in the nucleus and cytoplasm, affects Ras-signaling in cancers and nuclear localization may induce resistance to treatment." (PMID 22039439, 2011). "This provides new information into our understanding of the molecular mechanisms of cancer cell haematogenous dissemination and suggests that targeting the interaction of circulating galectin-3 with MUC1 in the circulation may represent an effective therapeutic approach for preventing metastasis." (PMID 20565834, 2010).